LGMN (legumain)
Diseases named in the same sentence as LGMN in open-access papers (continued):
Sharing a sentence is not in itself a finding about the gene and the disease.
tumor (continued). "Legumain is highly expressed and degrades fibronectin when remodeling the extracellular matrix in proximal tubules of the kidney, and it plays an important role in tumor growth/metastasis." (PMID 29541256, 2018). "Notably, legumain is synthesized as inactive zymogen in the tumour cells while mainly exists in the active form in macrophages, therefore imply a context-dependent action pattern of legumain in different cellular types." (PMID 27464733, 2016). "Thus, our data demonstrated that legumain was overexpressed by M2 polarized macrophages in the tumour microenvironment and the capacity of legumain to catabolize ECM components outside of the cell membrane." (PMID 27464733, 2016). "In addition, legumain was involved in angiogenesis and tumour progression via extracellular matrix (ECM) remodelling." (PMID 27464733, 2016). "Moreover, the expression level of legumain increased with expansion of the tumour, cleavage of the ECM and angiogenesis." (PMID 27464733, 2016). "Our study showed that the C9BC chimeric promoter could effectively activate downstream gene expression after exposure to 6 Gy of radiation and produce an RNAi effect for targeting LGMN to achieve an effective anti-tumor activity." (PMID 27656894, 2016). "Moreover, legumain secreted by M2 TAMs contributes to cleavage of the ECM as well as angiogenesis in tumour microenvironments." (PMID 27464733, 2016). "Thus, a direct coupling of reduced legumain content to reduced tumor load and effect of AndosanTM on legumain expression within tumors, remains elusive in the examined intestines." (PMID 28002446, 2016). "Additional studies are required to determine how legumain promotes tumor cell proliferation." (PMID 26607955, 2015). "However, in solid tumors, LGMN is overexpressed in tumors, the matrix, and endothelial cells in the tumor microenvironment." (PMID 26607955, 2015). "Legumain may represent a target for inhibition of tumor growth and metastasis based on its enhancement of tumor growth and its unique restricted specificity." (PMID 24023813, 2013). "Targeted drug delivery, achieved with a legumain inhibitor, proved to enhance drug delivery under hypoxia, a hallmark of the tumor microenvironment, but not under normoxia." (PMID 24014113, 2013). "Legumain, a member of the asparaginyl endopeptidase family, was considered to be overexpressed by TAMs, which may be a target for suppressing tumor growth." (PMID 22422103, 2012). "Legumain (LGMN) is an asparaginyl-specific cysteine endopeptidase that has been identified as a hypoxia-responsive gene and the combined use of LGMN inhibitor and PD-1 inhibitor could enhance anti-tumor efficacy." (PMID 41199316, 2025). "Legumain (LGMN), also known as asparaginyl endopeptidase, is a lysosomal cysteine protease that plays crucial roles in various physiological and pathological processes, including extracellular matrix remodeling, exosome-mediated chemical transport, and angiogenesis within the tumor microenvironment." (PMID 41375125, 2025). "In addition, circ‐LGMN (legumain) may also promote the development of GBM by targeting the miR‐127‐3p /LGMN axis, and circ‐LGMN can upregulate LGMN expression by sponging miR‐127‐3p, thus facilitating the proliferation and invasion of tumour cells and tissues." (PMID 36457281, 2023). "In addition, treatment with SAR131675 could reduce the number of macrophages that expressed LGMN at a high level and were immunocompromised in the tumor microenvironment." (PMID 36825203, 2023). "Based on subgroup marker genes, the cell cluster highly expressing LGMN was annotated as M2 cells, the cell cluster with high expression of CXCL9 was annotated as M1 cells, and the cell cluster highly expressing FABP4 was annotated as non-tumor-associated macrophages (NTAMs)." (PMID 36969247, 2023).
tumor (continued). "Our study displayed that MDA-MB-468 tumor-bearing mice, which owned high legumain expression, could be clearly visualized with high tumor uptake after the injection of [18F]SF-AAN, while PC-3 tumor-bearing mice showed almost background uptake in vivo at all the time point." (PMID 35631369, 2022). "Legumain (LGMN), also known as asparagine endopeptidase (AEP), is a lysosomal cysteine protease originally identified in the seeds of legumes, which is also present in the human body and is associated with a variety of tumor types at the stages of development, invasion and metastasis 14-16." (PMID 31892854, 2020). "Previous studies reported that inhibition/knock-down of legumain could suppress tumor progression." (PMID 29784082, 2018). "nRGD could specifically bind to legumain, present on tumor endothelial cells, tumor cells, and TAM." (PMID 28471401, 2017). "However, our study revealed co-staining of legumain and fibronectin in the tumour microenvironment." (PMID 27464733, 2016). "It is reported that high LGMN expression could facilitate metastasis and invasion of tumor cell." (PMID 27656894, 2016). "Furthermore, we determined the expression of legumain mRNA in the homogenates of tumour tissues." (PMID 27464733, 2016). "CST6 has a high binding affinity for Legumain (LGMN), a lysosomal cysteine protease involved in antigen processing, neuronal cell death, and tumour cell invasion." (PMID 40234537, 2025). "To confirm these findings in vivo, we treated the mice bearing CT2A tumors, where LGMN is highly expressed in TAMs, with WP1066 and AR-1014418, and analyzed the change of macrophages in tumor tissues using flow cytometry and IF." (PMID 40131864, 2025). "Legumain (LGMN), a lysosomal cysteine protease, is crucial for tumor progression, invasion, and metastasis, making it a promising target for cancer imaging and therapy." (PMID 41375125, 2025). "Among them, the TREM2+ subpopulation was characterized by high expression of GPNMB, TREM2, ACP5, LGMN, and TIMP2, and mainly distributed at the boundary and core region of the tumor." (PMID 38948071, 2024). "Recent studies have unveiled that a DNA vaccine targeting legumain can effectively stimulate CD8+ T cells to attack TAMs, leading to a significant reduction in TAM density within tumor tissues." (PMID 39717759, 2024). "Finally, to evaluate the diagnostic performance of LGMN for cancer, we drew a receiver operating characteristic (ROC) curve by using the pROC package to determine whether LGMN expression could enable to distinguish the 15 normal samples from the 103 tumor samples in the test set." (PMID 38980440, 2024). "Double-stained tumor neovascularization with CD31 and LGMN and found that LGMN was highly expressed in endothelial cells with the proliferation of neovascularization through flow cytometry analysis." (PMID 36825203, 2023). "Hsa_circ_0033009 (circLGMN) is derived from the mammalian legumain (LGMN) gene, which has been revealed to promote tumor progression." (PMID 37415736, 2023). "Three forms of legumain were observed in the tumor samples and were identified as the precursor form (prolegumain, 56 kDa), intermediate form (ACP, 46 kDa), and mature active form (AEP, 36 kDa)." (PMID 35800070, 2022). "Another protease enzyme that is over-expressed in the extracellular tumor microenvironment by stromal, TAM and endothelial cells in tumors is Legumain, making it potential stimulus in targeting the tumor stroma." (PMID 30429787, 2018). "Our results showed that 6 days of treatment with tumour homogenates induced M2 macrophage makers, CD163, IL-10 and MMP9 expression, as well as the expression of legumain in U937 cells." (PMID 27464733, 2016). "Furthermore, we found radiotherapy and targeted LGMN knockdown had synergistic effects in BC cells, so, knockdown of LGMN plus radiation treatment could enhance the therapeutic effects so as to gain more positive anti-tumor effects." (PMID 27656894, 2016).
tumor (continued). "Here, we report the discovery of a genuine ligase activity in human legumain (AEP) which has important roles in immunity and tumor progression that were believed to be due to its established cysteine protease activity." (PMID 25630877, 2015). "Together these data suggest that the mechanism through which CST6 induces apoptosis is due to its inhibition of LGMN activity and that TBX2 drives tumor growth through maintenance of LGMN activity." (PMID 24742492, 2014). "When tumor volume reached approximately 350 mm3 on day 10, mice were injected with PBS, NPs, Legumain-targeting HC-NPs (Leg-HC-NPs) (1 mM) and HC (100 μM) respectively at 3 days intervals within 15 days." (PMID 23825527, 2013). "Among the top 10 upregulated DEPs in tumor conditions were the enzymes IDO1 and LGMN." (PMID 40789452, 2025). "Our findings revealed that the protein levels of legumain were elevated in tumor tissues compared to their paired normal counterparts." (PMID 39948060, 2025). "In exploring the connection between LGMN and the AKT/p65 signaling axis, we observed that integrin αv is the receptor of LGMN on GBM cells that mediate LGMN’s function via activation of a downstream pro-tumor signaling axis, consistent with previous work." (PMID 40131864, 2025). "LGMN also shows high expression in TAMs, and the deletion of LGMN in TAMs can significantly accelerate tumor cell aging; however, the specific mechanisms are not yet clear." (PMID 39065799, 2024). "LGMN is a protein overexpressed both in TME and tumor cells." (PMID 38139241, 2023). "Legumain (LGMN) has been demonstrated to be overexpressed not just in breast, prostatic, and liver tumor cells, but also in the macrophages that compose the tumor microenvironment." (PMID 36825203, 2023). "Though we did not identify either the intensity or the percentage of legumain expression in any specific tumor type, we did find that non-mesenchymal tumors expressed an elevated level of legumain." (PMID 35203212, 2022). "We found that heightened signals of legumain were expressed in all canine tumor samples in the study, and, notably, the non-mesenchymal types of tumors harbored relatively high expression levels." (PMID 35203212, 2022). "The present study first compared the expression patterns of legumain in paraffin-embedded canine tumor tissues, with those of normal tissues, by immunohistochemistry." (PMID 35203212, 2022). "In contrast, group B showed no VDAC1-ΔC in tumor (T) tissues in parallel with weak or absent expression of LGMN." (PMID 32194829, 2020). "We found that knockdown of LGMN could downregulate the expression of MMP2 and MMP9, which could break down extracellular matrix and promote tumor metastasis." (PMID 27656894, 2016). "The remaining four studies reported that LGMN overexpression was not related to tumor differentiation." (PMID 26607955, 2015). "These factors share a common characteristic in that they do not effect tumor progression, suggesting that LGMN’s function in cancer was limited to tumor progression, unless other mechanisms were involved." (PMID 26607955, 2015). "In contrast to M1 macrophages that do not express legumain and have immune-surveillance anti-tumor activity, most TAMs are polarized M2 macrophages that promote tumor growth and angiogenesis." (PMID 21385454, 2011). "The use of a DNA vaccine against Asparaginyl Endopeptidase Legumain (which is overexpressed in TAMs) demonstrated a reduction in the number of TAMs in the TME of BC in syngeneic BALB/c mice and led to a decreased rate tumor growth, angiogenesis, and metastasis." (PMID 39941714, 2025). "Even though no direct evidence of a connection between tumor development and legumain expression has been widely presented, we speculate that these characteristics may explain why legumain was overexpressed, especially in the epithelial tumors." (PMID 35203212, 2022).
tumor (continued). "Therefore, the nanoparticle (PPP) collapsed when it encountered the weakly acidic tumor microenvironment where PTX molecules fell off, and further triggered the cleavage of the peptide substrate by legumain that is highly expressed in tumor stroma and tumor cell surface." (PMID 35638851, 2022). "The mechanism of radiation-induced knockdown of LGMN suppressing cell migration and invasion was next investigated with a focus on MMP9 and MMP2, a kind of gelatinase has the unique ability to degrade extracellular matrix components and facilitate tumor migration and invasion." (PMID 27656894, 2016). "The tumor aggressiveness in these patients could be the result of the combination of a switch to EMT process activation, re-expression or maintenance of the primary cilium, together with a decrease in VDAC1 and LGMN expression and thus the disappearance of the cleaved form of VDAC1." (PMID 32194829, 2020). "Even though the direct correlation between tumor progression and legumain has not been widely described, the presence of cysteine endopeptidases, such as cathepsins B and L, which are activated by the legumain-mediated hydrolysis of asparaginyl bonds, may contribute to tumor malignancy." (PMID 35203212, 2022). "Moreover, treatment with the LGMN inhibitor C11 in CT2A and 005 GSC tumor–bearing mice did not affect intratumoral Ki67+F4/80+ proliferating macrophages." (PMID 40131864, 2025).
cancer (55 papers, 2013 to 2026). A tumor composed of atypical neoplastic, often pleomorphic cells that invade other tissues. "Aberrant levels of the asparaginyl endopeptidase legumain have been linked to inflammation, neurodegeneration, and cancer, yet our understanding of this protease is incomplete." (PMID 38199506, 2024). "LGMN is involved in normal biological processes, but it has also been linked to several pathologies, including cancer." (PMID 36825203, 2023). "The up-regulation of legumain is highly associated with cancer invasion, metastasis and angiogenesis." (PMID 35631369, 2022). "LGMN is ubiquitously expressed, yet it was reported to be increased in various types of cancers, in neurodegenerative diseases and in macrophages associated with inflammatory diseases." (PMID 35053409, 2022). "Furthermore, it has been demonstrated that Legumain is associated with various diseases, including cancer, neurodegenerative diseases, and so on." (PMID 38057699, 2023). "In addition, forced LGMN expression was associated with poorer prognosis in several cancers." (PMID 39065799, 2024). "Collectively, our results inform future mechanistic studies on legumain in the gut, especially its implications in cancer development, and allow comparison of mouse models of acute colitis with human mucosal biopsies." (PMID 39392222, 2025). "The mammalian lysosomal protease legumain is often dysregulated in pathophysiological conditions including inflammation, neurodegeneration, and cancer, yet its proteolytic targets are poorly defined." (PMID 40970443, 2025). "Among them, legumain, an asparagine-specific endopeptidase, has been shown to promote cancer by modulating the cancer immune microenvironment." (PMID 40227215, 2025). "GSEA results demonstrated that cancer cell proliferation signatures were the top hits downregulated in tumors with low LGMN expression in TAMs, suggesting a connection between TAM-derived LGMN and cancer cell proliferation in GBM." (PMID 40131864, 2025). "Overexpression of legumain has been observed in various cancer types and is correlated with increased malignancy and poor prognosis." (PMID 39948060, 2025). "Through binding to cell surface integrin αvβ3 via an RGD motif, the autocrine pro-legumain activates FAK-Src-Ras homolog family member A (RhoA) signaling in cancer cells." (PMID 41294885, 2025). "With reference to myeloid cells and consistent with previous reports 26, 27, we identified LGMN+ and SPP1+ TAM clusters in our data, with a particular association with cancer cells." (PMID 38169544, 2024). "For instance, a recent meta-analysis showed that LGMN was overexpressed in cancer compared to normal tissues and its level was higher in phase III–IV diseases than phase I–II diseases." (PMID 38980440, 2024). "Legumain (or asparagine endopeptidase/AEP) is a lysosomal cysteine endopeptidase associated with increased invasive and migratory behavior in a variety of cancers." (PMID 38582932, 2024). "Legumain activity is upregulated in a range of diseases, including Alzheimer’s and Parkinson’s diseases, pancreatitis, and cancer." (PMID 38199506, 2024). "Accordingly, targeted inhibition of LGMN by silencing RNAs (siRNAs) resulted in decreased cancer cell proliferation." (PMID 38139241, 2023). "Here, we reported, for the first time, that legumain, a widely-used cancer biomarker in human oncology, is also significantly expressed in ten types of canine neoplasms." (PMID 35203212, 2022). "Legumain is the endopeptidase which specifically cleaves linkers containing asparagine or aspartic acid residues which are upregulated in the various cancer cells lysosomal compartments." (PMID 35331246, 2022). "LGMN is an asparagine endopeptidase highly expressed in multiple solid tumors that plays an essential role in cancer, immunity, and neurodegenerative diseases." (PMID 36496076, 2022).